SPTB (spectrin beta, erythrocytic)
Diseases named in the same sentence as SPTB in open-access papers (continued):
Sharing a sentence is not in itself a finding about the gene and the disease.
cancer (4 papers, 2014 to 2023). A tumor composed of atypical neoplastic, often pleomorphic cells that invade other tissues. "The MSigDB Cancer Neighborhood highlighted cancer-associated genes, TAL1, ANK1, SPTB, SPTA1, PRDX2, MAP2K3, etc.." (PMID 25522020, 2014). "Furthermore, spectrin beta chain (SPTB) also showed differential expression between SCLC and all other cancer tissue." (PMID 35681609, 2022).
tumor (3 papers, 2016 to 2023). "Tumor-associated reductions in SPTB were associated with similar reductions in SPTA1 (70%), SLC4A1 (60%), and ANK1 (70%) in tumor tissue when compared to control tissue." (PMID 27799870, 2016). "SPTB was determined to be the single most discriminatory protein of adenocarcinoma displaying a 70% reduction in tumor tissue relative to control tissue." (PMID 27799870, 2016). "These are preliminary results based on a small cohort, however, the results suggest that the tumor tissue-derived proteins (HSPA4, SPTB and NIPSNAP1) and a combination of HSPA4 and SPTB, could achieve relatively high predictive ability for nCRT sensitivity." (PMID 35292026, 2022). "HSPA4, SPTB and NIPSNAP1 in tumor biopsies and/or their optional combinations might be potential predictive markers for nCRT response in patients with LARC." (PMID 35292026, 2022).
adenocarcinoma (1 paper, 2016). A common cancer characterized by the presence of malignant glandular cells. "The adenocarcinoma-dependent reduction in SPTB was also consistently observed in 82% of subjects." (PMID 27799870, 2016). "Reductions in SPTA1 and SPTB were indirectly associated with APEX1, which showed a 2.7-fold increase in adenocarcinoma compared to non-malignant tissue and was consistently elevated in 82% of subjects." (PMID 27799870, 2016).
connective tissue disorder (1 paper, 2014). A disease involving the connective tissue. "The top ranked disease functions involved with PPROM were inflammatory processes while the top disease functions involved with sPTB were connective tissue disorders." (PMID 25264875, 2014). "In addition, connective tissue disorders have different components in sPTB and pPROM." (PMID 25264875, 2014).
infectious disease (1 paper, 2022). A disorder directly resulting from the presence and activity of a microbial, viral, or parasitic agent in humans. "For example, a woman with a low BMI may also be zinc deficient, of short stature, or have an infectious disease, all with associated risks for sPTB." (PMID 35356651, 2022).
metabolic disorders (1 paper, 2024). "Recent evidence has shown a strong association between metabolic disorders and sPTB." (PMID 39229380, 2024). "In sPTB, several functional disruptions, including apoptosis, senescence, and metabolic disorders, are observed in the placenta." (PMID 39229380, 2024). "To more precisely determine the role of placental metabolic abnormalities in sPTB, we excluded patients with known maternal metabolic disorders." (PMID 39229380, 2024). "Besides, many metabolic disorders were observed in placenta of sPTB." (PMID 39229380, 2024).
neurological disorders (1 paper, 2022). "In addition, mutations in various members of the spectrin gene family are associated with erythroid cell disorders (SPTA1, SPTB) and neurological disorders (SPTAN1, SPTBN1, SPTBN2, and SPTBN4); however, no human genotype-phenotype correlation has been established for SPTBN5 to date." (PMID 35782384, 2022).
SPTB also shares sentences with these, for which no sentence is quoted: Duchenne muscular dystrophy (7 papers); neonatal hemolytic anemia (3); Spherocytosis (3); genetic disease (2); pregnancy (2); Splenomegaly (2); Achalasia (1); adolescent idiopathic scoliosis (1); Alagille syndrome (1); asthma (1); atrial septal defect (1); Cachexia (1); cervical cancer (1); cholelithiasis (1); Cirrhosis (1); coronary heart disease (1); dystrophinopathy (1); endometriosis (1); Fuchs endothelial corneal dystrophy (1); hemoglobinopathies (1); Hepatic fibrosis (1); Hyperbilirubinemia (1); Hypercholesterolemia (1); hyperlipidemia (1); Infertility (1); inflammation (1); inflammatory bowel disease (1); iron overload (1); kidney failure (1); lipid metabolic disorders (1).
A further 16 diseases each share a sentence with SPTB in 1 paper.